MLKL (mixed lineage kinase domain like pseudokinase)
Diseases named in the same sentence as MLKL in open-access papers (continued):
Sharing a sentence is not in itself a finding about the gene and the disease.
kidney (6 papers, 2019 to 2023). "In kidney injuries, miR-500a-3p is thought to mitigate the toxicity and ischemic damage caused by necroptosis and inflammatory responses by targeting the MLKL and RIPK3 proteins according to experiments in HK2 cells." (PMID 36991314, 2023). "However, we previously demonstrated that MLKL-deficient mice are partially but significantly protected in the kidney IRI model and discussed a direct effect of necroptosis in kidney tubules." (PMID 35288534, 2022). "MLKL KO mice and WT controls were used to investigate the role of MLKL in regulating liver IR injury." (PMID 36765043, 2023). "MLKL knockout (KO) attenuated liver IR injury and suppressed the activation of cGAS-STING signaling in intrahepatic macrophages, which was abrogated by STING activation with its agonist." (PMID 36765043, 2023). "Next, a STING-specific agonist, DMXAA, was used to determine the critical role of macrophage STING inhibition in protecting against liver IR injury by MLKL depletion." (PMID 36765043, 2023). "In this study, we investigated the role of MLKL in regulating the interplay between hepatocyte injury and macrophage pro-inflammatory responses during liver IR injury." (PMID 36765043, 2023). "MLKL deficiency promoted mitophagy activation to reduce oxidative DNA injury in hepatocytes, which suppressed the activation of cGAS-STING signaling in macrophages, leading to attenuated liver IR injury." (PMID 36765043, 2023). "Therefore, targeting of endothelial MLKL during chronic liver injury could potentially alleviate fibrosis." (PMID 37511074, 2023).
metabolic disease (6 papers, 2018 to 2025). A congenital disorder (due to inherited enzyme abnormality) or acquired (due to failure of a metabolically important organ) disorder resulting from an abnormal metabolic process. "From a clinical perspective, only a limited number of human diseases, including metabolic disorders, have been associated with variant sequences of MLKL to date." (PMID 38195700, 2024). "Together, the mediators of necroptosis (RIP1, RIP3, and MLKL) likely function through distinct mechanisms in metabolic diseases." (PMID 38195700, 2024). "Given the significant and distinct roles of the RIP1-RIP3-MLKL axis in metabolic diseases of various etiologies, researchers have investigated the potential of circulating concentrations of RIP1, RIP3, and MLKL as potential biomarkers in humans." (PMID 38195700, 2024). "Since nutrition is another important driver of genetic adaptation in humans, exploring the role of MLKL S132P in metabolic disease is also of interest." (PMID 37770424, 2023). "MLKL is induced and activated by different high-fat diets in murine models of metabolic disease." (PMID 38195700, 2024). "Moreover, MLKL concentrations were not related to disease severity, as assessed by correlation with the APACHE-II score, or the presence of concomitant metabolic diseases, which had been previously linked to elevated MLKL levels in non-ICU populations." (PMID 29606984, 2018). "A large body of evidence places RIPK1/3-driven caspase-8 or MLKL signaling upstream of NLRP3 inflammasome activity in a range of disease settings, yet their contribution to inflammasome activity in metabolic disease is less clear." (PMID 39532538, 2025). "Such investigations will shed further light on whether the absence of MLKL alone is sufficient to affect metabolic disease or if other genetic or environmental factors are also involved in disease development." (PMID 38195700, 2024).
neurological diseases (6 papers, 2017 to 2023). "Necrostatin-1 (Nec-1), a specific RIP1 kinase inhibitor, has been used to block the necroptotic RIP1/RIP3/MLKL pathway and has been shown to be effective in several neurological diseases." (PMID 36991017, 2023). "RIPK1, RIPK3, and MLKL play a pivotal role in inducing necroptosis, and RIPK1, RIPK3, and MLKL upregulation could be common in many neurological diseases, including CIR injury." (PMID 34905731, 2021). "Evidence is rapidly accumulating for the role of MLKL in mouse models of neurological disease." (PMID 34071602, 2021).
infectious disease (4 papers, 2018 to 2024). A disorder directly resulting from the presence and activity of a microbial, viral, or parasitic agent in humans. "Small molecules that inhibit necroptosis by targeting the kinase activity of RIPK1, one of the main upstream conduits to MLKL activation, have shown promise in several murine models of non-infectious disease and in phase II human clinical trials." (PMID 34071602, 2021). "Genetic and experimental models of disease provide a strong rationale that MLKL and necroptosis are important mediators and modifiers of infectious and non-infectious disease." (PMID 34071602, 2021). "Manipulating RIPK3/MLKL-mediated necroptosis may represent novel therapeutic targets, not only for RAP but also for other E. faecalis-associated infectious diseases." (PMID 35708336, 2022).
adenocarcinoma (3 papers, 2015 to 2022). A common cancer characterized by the presence of malignant glandular cells. "Two alternatively spliced isoforms of MLKL were reportedly expressed by HT-29 colon human adenocarcinoma cells." (PMID 26704887, 2015). "This suggests a potential role of MLKL-dependent cell death in development of adenocarcinoma." (PMID 35422482, 2022).
cardiovascular diseases (3 papers, 2024 to 2026). "Mixed lineage kinase domain-like protein (MLKL), a key effector of necroptosis, has been implicated in cardiovascular disease; however, its role in MI remains incompletely defined." (PMID 42042040, 2026). "The RIP3/MLKL pathway is a well-established necroptotic pathway that has been extensively studied and demonstrated in a variety of cardiovascular diseases." (PMID 39329120, 2024).
inflammation (3 papers, 2021 to 2025). Aberrant reaction of the microcirculation characterized by movement of fluid and leukocytes from the blood into extravascular tissues. "Our findings challenge prior studies regarding MLKL’s involvement in liver inflammation in diet-induced MAFLD and the role of necroptosis-induced liver inflammation in fibrosis." (PMID 38474061, 2024).
bone disorder (1 paper, 2021). "In this study, we found that the RIPK1/RIPK3/MLKL pathway was involved in alcohol-induced bone disorders and osteoblast necroptosis both in vivo and in vitro." (PMID 34745415, 2021).
brain disease (1 paper, 2021). "Besides, numerous studies have shown that MLKL-dependent necroptosis is critical in the pathogenesis of brain diseases, especially ischemic brain injury and neurodegenerative diseases." (PMID 33064829, 2021).
inflammatory myopathy (1 paper, 2025). "Importantly, inhibition of necroptosis with necrostatin-1 and knockdown of MLKL expression successfully prevented cells from undergoing necroptosis-induced cell death, suggesting that targeting necroptotic pathways could be a noteworthy therapeutic strategy in inflammatory myopathy treatment." (PMID 40943287, 2025).
intestinal disease (1 paper, 2019). "However, we did not consider the potential effect of MLKL deficiency on intestinal microbiota composition, which may affect intestinal disease symptoms." (PMID 31024858, 2019).
MLKL also shares sentences with these, for which no sentence is quoted: myocardial ischemia (5 papers); chronic periodontitis (3); enteritis (3); fibrosis (3); head and neck squamous cell carcinoma (3); histiocytic lymphoma (3); acute myocardial infarction (2); alcoholic liver diseases (2); autoimmune hepatitis (2); carotid atherosclerosis (2); chronic recurrent multifocal osteomyelitis (2); Dry skin (2); Gaucher disease (2); liver (2); lupus nephritis (2); abdominal aortic aneurysm (1); acne (1); acute liver failure (1); acute monocytic leukaemia (1); acute tubular necrosis (1); alcohol (1); ankylosing spondylitis (1); autoimmune myocarditis (1); autoinflammatory syndrome (1); bacterial pneumonia (1); biliary atresia (1); bronchopulmonary dysplasia (1); Cholestatic liver disease (1); Crohn disease (1); dilated cardiomyopathy (1).
A further 65 diseases each share a sentence with MLKL in 1 paper.